ABCA1 (ATP binding cassette subfamily A member 1)
Diseases named in the same sentence as ABCA1 in open-access papers (continued):
Sharing a sentence is not in itself a finding about the gene and the disease.
tumor (continued). "Additionally, high-level expression of ABCA1 in primary tumors of serous ovarian cancer was associated with reduced survival of the patients and enhanced tumor cell growth and migration." (PMID 33562440, 2021). "Deficiency in either ABCA1 or ABCG1 in macrophages attenuates tumor growth in xenograft models." (PMID 30283400, 2018). "Moreover, cholesterol efflux function has been linked to anti-tumour activity, and thus ABCA1 is considered as a tumour-suppressor molecule." (PMID 24646941, 2014). "Therefore, we speculate that ABCA1 overexpression in tumor-associated macrophages may mediate the tumor-promoting effects of these signaling pathways within the TME." (PMID 37874419, 2023). "This contradicted the findings that both high ABCA1 expression and high cholesterol are tumor-promoting factors." (PMID 41540015, 2026). "Functionally, they engulf myelin debris from the tumor microenvironment and export lipids to mesenchymal-like GBM cells via an LXR/ABCA1-dependent mechanism, supporting tumor metabolic demands and enhancing proliferation." (PMID 40862760, 2025). "In NB, ABCA1-mediated cholesterol efflux protects tumor cells from oxidative stress, facilitating survival under metabolic stress." (PMID 40370434, 2025). "APOE overexpression significantly reduced tumor cell proliferation and invasion, both in vitro and in vivo, by activating the ABCA1‐LXR axis." (PMID 39810624, 2025). "We further performed immunohistochemical analysis to assess APOE and ABCA1 expression in tumour tissues." (PMID 39810624, 2025). "While exogenous cholesterol alone had minimal direct effects on macrophages, it synergized with tumor-derived factors to further increase ABCA1 expression, promoting macrophages with stronger immunosuppressive characteristics." (PMID 40270603, 2025). "Using normal tissues in the GTEx dataset as controls, we investigated the differences in the expression of ABCA1 between normal tissues and tumour tissues." (PMID 40297807, 2025). "GPNMB-positive macrophages promote tumor cell proliferation and sphere-forming capability by transferring myelin-derived cholesterol and fatty acids to tumor cells through an LXR/Abca1-dependent pathway." (PMID 41180454, 2025). "The estimated filtration values of cancer-associated fibroblasts from BLCA, CESC, BRCA-LumA, PRAD, HNSC, and HNSC (human papillomavirus +/-) tumour samples were statistically positive for ABCA1 expression." (PMID 40297807, 2025). "Our results demonstrated that APOE overexpression was accompanied by increased ABCA1 expression in tumour tissues." (PMID 39810624, 2025). "ABCA1 and ABCG1 regulate cholesterol efflux and influence immune responses: ABCA1 deficiency impairs T cell receptor signalling, while ABCG1 loss promotes an anti-tumor M1 macrophage phenotype." (PMID 41432903, 2025). "Conversely, ABCA1 was markedly reduced (log2FC = −3.41, padj = 2.78 × 10−13), implicating cholesterol efflux dysregulation in tumor metabolism." (PMID 41373405, 2025). "In tumours, both AMɸ and AIMɸ upregulated genes involved in cholesterol and lipid transport and metabolism (such as ABCA1, APOC1, APOE, FABP3 and FABP5) compared to the background tissue." (PMID 38782901, 2024). "This will include, but is not limited to, assessing the specific effects of ABCA1 on tumor growth, metastasis, and the tumor immune microenvironment in vivo." (PMID 39749197, 2024). "In the ω-3 group, GPR120 WT BMD M2-like macrophages infiltrating the tumor were significantly reduced in number and gene expression of cholesterol transporters Abca1, Abca6, and Abcg1." (PMID 37872251, 2024). "Remarkably, while ABCA1 can promote metastasis through these mechanisms, it also exerts an inhibitory effect on tumor development by suppressing cell proliferation, highlighting the dual function of ABCA1 in regulating both proliferation and metastasis." (PMID 39000236, 2024).
tumor (continued). "The results showed that the ABCA1 expression level in the liver metastatic nodules was significantly higher than that in the adjacent normal tissues and primary tumours by IHC staining for ABCA1." (PMID 38385857, 2024). "The EV–DOCK7/ABCA1 regulatory axis links cholesterol metabolism and tumour metastasis in CRC via TAM‐EVs." (PMID 38385857, 2024). "Nevertheless, some research found that ABCA1/ABCG1 had a distinct involvement in the polarization of macrophages during tumor progression." (PMID 38540127, 2024). "Relatedly, we also examined expression levels of known LXR target genes and found that SREBP1c, ACC, and SCD transcript levels were elevated in the tumor tissues, while ABCA1 levels were decreased." (PMID 36830714, 2023). "The survival analysis of the CGGA cohort also suggested that 3D models can better simulate the increased difficulty of drug delivery to GBM tumours, where patients with increased ABCA1 expression experience lower survival probabilities." (PMID 37237462, 2023). "The relationships between ABCA1 expression and anti-tumor drug sensitivity and immune checkpoints were also explored." (PMID 37874419, 2023). "Among the eight tumor-related genes, ABCA1 and PLA2G7 were found to be significantly related to TNF." (PMID 36843944, 2023). "We observed the expression of ABCA1 and SCD mainly in tumor-associated macrophages (cluster 2), while HMGCR was mainly expressed in DCs." (PMID 36792589, 2023). "ABCA1 exerts tumor-promoting effects in GAC, with its high expression associated with malignant phenotypes and poor prognosis." (PMID 37874419, 2023). "Because cancer cells are closely related to intracellular cholesterol levels and ABCA1 functions as a reverse cholesterol transport channel, the role of ABCA1 in the regulation of cellular processes involved in tumor behavior remains controversial." (PMID 36672209, 2023). "Cholesterol dysregulation is linked to tumour development, hence proper regulation of its level is fundamental and the ABCA transporters (namely ABCA1, A8 and A12) are known to function in the transport of cholesterol." (PMID 36674859, 2023). "Our study revealed that ABCA1/G1 expression was predominantly found in GBM tumor tissues, particularly in TAMs, making it an ideal target for manipulating cholesterol efflux." (PMID 37474548, 2023). "Taken together, ABCA1 expression appears to correlate with less tumor initiation and proliferation, but more progression and resistance, although a definitive mechanism has not yet been established." (PMID 35327383, 2022). "In conclusion, our data indicate that the HDL cholesterol efflux capacity and therefore its antitumor activity is regulated by the HDL particle composition and/or the expression pattern of cell surface receptors such as SR-B1 and ABCA1 on tumor cells." (PMID 35577388, 2022). "Since high ABCA1 expression is associated with worse outcome in EOCs, we wanted to identify cell lines that expressed levels of ABCA1 representative of tumours from patients with poor outcomes." (PMID 35454786, 2022). "Genes that were differentially expressed between EOC tumours with high and low ABCA1 expression levels were determined and enriched to identify pathways and biological processes related to high ABCA1 expression in EOC." (PMID 35454786, 2022). "In IHC of brain tissue from GL261 tumor-bearing mice, we identified that the expression level of ABCA1 in tumor tissue was higher than that in normal brain tissue." (PMID 36248907, 2022). "ABCG1, for example, is known to efflux cholesterol, and expression of both ABCA1 and ABCG1 are needed to deplete lipid rafts in tumour-associated macrophages." (PMID 35454786, 2022). "With tumor progression, the expression level of ABCA1 in TAMs was positively correlated with the population of TAMs in tumor tissue." (PMID 36248907, 2022).
tumor (continued). "ABCA1 was identified as a tumor suppressor, as it favors the execution of cell death programs via mitochondrial pathways and limits AKT signaling by regulating the lipid composition in the plasma membrane." (PMID 34502100, 2021). "In one study, upregulation of RASSF1C in tumor cells downregulates miR-33a, consequently upregulating ABCA1." (PMID 34281263, 2021). "A cholesterol-lowering drug, simvastatin, was able to repolarize tumor-associated macrophages (TAM), promoting the M2-to-M1 phenotype switch via cholesterol-associated liver X receptor (LXR)/ATP-binding cassette transporter A1 (ABCA1) regulation." (PMID 34576042, 2021). "Individuals with upregulation of ABCA1 expression have an improved risk of CRC recurrence and OS independently of tumor stage." (PMID 33194695, 2020). "Until now, sporadic observations correlated ABCA1 to pro-tumor or tumor-suppressive functions in solid cancers." (PMID 32155954, 2020). "In contrast, silencing of PPARβ/δ in prostate cancer cell lines inhibited tumor cell proliferation and tumor growth, which was attributed to activation of the ABCA1 cholesterol transporter-Caveolin1-TGFβ receptor signaling axis." (PMID 32375405, 2020). "Being ABCA1 almost undetectable in tumour cells, silencing experiments targeting this transporter were not performed." (PMID 29396407, 2018). "This synergistic action further verified that the PPARγ/LXRα/ABCA1 pathway played an important role in the anti‐tumor proliferative effect of efatutazone." (PMID 29573196, 2018). "The ABCA1 expression is clearly associated with two indicators of CRC outcome: DFS and OS, in patients of all tumor stages." (PMID 29464044, 2018). "In contrast, while the lipoprotein transporter APOE was variably regulated by density across cell lines, the cholesterol efflux pump ABCA1 was significantly upregulated in both the normal and tumor lines at high densities." (PMID 28118603, 2017). "The observation that animals with myeloid deficiency of ABCA1 (A1−M/−M) and or ABCG1 (G1−M/−M) transporters had smaller B16F10 tumors and reduced accumulation of tumor-infiltrating MDSCs is, at present, only associative." (PMID 29069761, 2017). "For example, in prostate cancer cells inhibition of ABCA1, which effluxes cholesterol, resulted in tumor progression." (PMID 29069761, 2017). "Further investigation into the role of MDSCs in mediating the observed influence of myeloid Abca1 gene in tumorigenesis are needed to prove a specific role of this cell type in the observed effects on tumor growth." (PMID 29069761, 2017). "Further, mice with myeloid-specific deletion of Abca1 (A1−M/−M) were protected against tumor development in relatively young (3-4 months old) animals on normal chow diet." (PMID 29069761, 2017). "Further in vivo experiments also demonstrated that significant increased tumor growth was observed in ABCA1-depleted HeyC2 cells as compared to control." (PMID 25628764, 2015). "Therefore, we conducted a comprehensive study of the ABCA1 gene in different tumours on the basis of data from the TCGA, CPTAC, and GEO databases, as well as molecular characterization of gene expression, gene alterations, and protein phosphorylation." (PMID 40297807, 2025). "Although the molecular basis underlying this discrepancy remains to be fully elucidated, these differences may reflect tumor-specific downstream signaling or microenvironmental factors that modulate ABCA1 function." (PMID 40370434, 2025). "However, there is still no reliable evidence confirming the pan-cancer relationship between ABCA1 and various tumour types on the basis of clinical big data indicators." (PMID 40297807, 2025). "The potential value of ABCA1 was also mined, such as: ABCA1 may be a potential marker of tumor metastasis, play a role in cancer resistance, and its expression may inhibit the spread of tumor cells." (PMID 40297807, 2025).
tumor (continued). "The data showed that the “organophosphate biosynthetic process” may be closely related to the effect of ABCA1 on tumour pathogenesis." (PMID 40297807, 2025). "We observed ABCA1 gene changes in different tumour samples in the TCGA cohort." (PMID 40297807, 2025). "In this study, ABCA1 was highly expressed in most tumour tissues compared with normal tissues." (PMID 40297807, 2025). "ABCA1 may also affect immune cell function by regulating cholesterol levels in the tumour microenvironment, helping tumours evade immune surveillance." (PMID 40297807, 2025). "TAM-EVs primarily affect tumor cells to undergo EMT by upregulating ABCA1 expression in MC-38 and CT-26 cells, decreasing cell membrane and intracellular cholesterol content, and potentially increasing membrane fluidity, which is closely associated with tumor cell metastasis." (PMID 40034694, 2025). "We integrated tumour samples and normal samples from the TCGA database, analysed the expression levels of ABCA1 in each TCGA cancer type, and determined the expression characteristics of ABCA1 mRNA using the TIMER2 method." (PMID 40297807, 2025). "Therefore, the expression level of ABCA1 has a certain degree of influence on the development, treatment and prognosis of GBM tumours; however, further study of the role of ABCA1 in the treatment of GBM tumours is still needed." (PMID 40297807, 2025). "Meanwhile, the Kaplan-Meier curve showed that a low expression level of ABCA1 was accompanied by a better prognosis, suggesting that ABCA1 may be a tumor suppressor gene, which accorded with the logic that upstream ALKBH5 plays as a potential oncogene." (PMID 38481816, 2024). "Survival analysis indicated that high expression of ABCA1 in SKCM was associated with better prognosis and might exist as a tumor suppressor gene." (PMID 38481816, 2024). "Genetic deletion of Abca1 and Abcg1 eliminates tumor-promoting TAMs and slows tumor progression." (PMID 39857239, 2024). "Based on the results of our study and previous reports, we may reasonably speculate that the epigenetic modification of ABCA1 mediated by m6A demethylase ALKBH5 may affect tumor progression of SKCM via modulating cellular cholesterol homeostasis and autophagy." (PMID 38481816, 2024). "T0901317 can also inhibit tumor cell proliferation through the PPARγ-LXRα-ABCA1 pathway." (PMID 38630355, 2024). "However, several investigations have revealed that ABCA1 is a tumor suppressor gene that encourages cholesterol metabolism for the inhibition of cancer progression." (PMID 38827789, 2024). "Previous studies have shown that ABCA1 plays dual roles across tumour types." (PMID 38385857, 2024). "HDL can alter the tumor microenvironment by modulating lipid content, especially by mediating excess cholesterol removal by ABCA-1, ATP-binding cassette transporter G-1 (ABCG-1), and scavenger receptor class B type 1 (SR-B1) through reverse cholesterol transport." (PMID 39195217, 2024). "To clarify whether ABCA1 participated in ALKBH5-dependent tumor progression and metastasis, we silenced ABCA1 in ALKBH5 stable knockdown SKCM A375 and A2058 cells." (PMID 38481816, 2024). "Moreover, IHC analysis of ABCA1 in patients with liver‐metastatic CRC indicated that ABCA1 expression is significantly greater in metastatic liver nodules than in primary CRC tumours." (PMID 38385857, 2024). "ABCA1 expression is altered in many types of tumors and the consequences may vary depending on the tumor type." (PMID 37312227, 2023). "Notably, the expression levels of ABCA1/G1 were over ~17-fold higher in tumor-infiltrating macrophages than in peripheral macrophages, indicating that cholesterol metabolism is under upward pressure in TAMs." (PMID 37474548, 2023). "Furthermore, ABCA1 expression negatively correlated with plasma cells and T helper cells; plasma cells have a positive role in anti-tumor immunity." (PMID 37874419, 2023).
tumor (continued). "Their research provided evidence suggesting that the restoration of ABCA1 expression could inhibit tumor development." (PMID 37627777, 2023). "Moreover, tumor-related studies have found that ABCA1-mediated intracellular cholesterol homeostasis is altered in cancer cells, affecting membrane-anchored signaling pathways." (PMID 37874419, 2023). "In that research, it was observed that cells that overexpress ABCA1 had a lower level of E-CAD and a higher level of VIM; this confirmed that ABCA1 could promote tumour progression by promoting EMT and cell migration." (PMID 36674859, 2023). "The tumour suppressive effects of ABCA1 could be attributed to its role in reducing mitochondrial cholesterol levels under conditions of increased cholesterol synthesis." (PMID 37345165, 2023). "ATP-binding cassette A1 (ABCA1) is a potential prognostic marker for various tumor types." (PMID 37874419, 2023). "Moreover, we have identified HMGCR and ACAT1 expression in the tumor region as possible markers for tumor progression and ABCA1 as anti-cancer gene in LUAD." (PMID 37024569, 2023). "ABCA1 suppresses tumor growth by mediating cholesterol efflux in tumor cells to promote cell death." (PMID 37545500, 2023). "Moreover, existing studies have reported that overexpressed ABCA1 facilitates tumor cell proliferation, tumor growth, and acquired chemotherapy resistance in multiple tumors." (PMID 37749600, 2023). "Furthermore, in the distribution analysis of ABCA1 expression on tumor cells and tumor-infiltrating immune cells, we found that the expression level of ABCA1 in TAMs was significantly higher than that in TILs and monocytes." (PMID 36248907, 2022). "Thus, downregulation of ABCA-1 results in high cholesterol levels inside the cells, leading to tumor progression." (PMID 36480560, 2022). "This analysis suggests that high expression levels of ABCA1 could be impacting upon the cholesterol pathway in poor outcome tumours." (PMID 35454786, 2022). "Importantly, tumor cholesterol efflux genes such as ABCA1, ABCG1 and the master regulator LXRs were also induced by XY018 treatment." (PMID 35804882, 2022). "On the other hand, cancer cells can modulate ABCA1 expression in tumor infiltrating immune cells." (PMID 34502100, 2021). "Moreover, while most studies suggest that ABCA1 activity is protective of cancer progression, there is also evidence of ABCA1 facilitating cell proliferation and tumor growth." (PMID 33562440, 2021). "Regulation of BTN3A1 stability together with protein trafficking and expression of the transporter ABCA1 within tumor microenvironment, as shown for doxorubicin, may be crucial to trigger optimal cross-talks between DCs and γδ T cells." (PMID 32435249, 2020). "In conclusion, Apo A1 has several roles on different aspects of tumor progression and might inhibit tumor growth by downstream ABCA1/ABCG1 activation." (PMID 31598156, 2019). "We have recently reviewed the potential role of ABCA1 on tumor development." (PMID 31311983, 2019). "However, some studies revealed that ABCA1/ABCG1 had different role in tumor progression involving macrophage polarization." (PMID 31598156, 2019). "We found that exonic variants of ABCA1 gene could be associated with CRC outcome as well as age of tumor development, tumor grade, vascular invasion and perineural invasion." (PMID 29464044, 2018). "Moreover, individuals with upregulation of ABCA1 and AGPAT1 expression have an increased risk of CRC recurrence, independently of tumor stage." (PMID 29464044, 2018). "The recently observed anti-tumor phenotype with Abcg1 deficiency was also noted to be accompanied by enhanced Abca1 expression in TAMs, though the potential role of ABCA1 was not examined." (PMID 29069761, 2017).